FAM89B (family with sequence similarity 89 member B)
Description:
Negatively regulates TGF-beta-induced signaling; in cooperation with SKI prevents the translocation of SMAD2 from the nucleus to the cytoplasm in response to TGF-beta. Acts as an adapter that mediates the specific recognition of LIMK1 by CDC42BPA and CDC42BPB in the lamellipodia. LRAP25-mediated CDC42BPA/CDC42BPB targeting to LIMK1 and the lamellipodium results in LIMK1 activation and the subsequent phosphorylation of CFL1 which is important for lamellipodial F-actin regulation.
Synonyms: Lrap25; MTVR1; MTVR
Tractability: No criterion of Open Targets' tractability assessment is met for any kind of drug.
Gene: Protein-coding gene on chromosome 11 (65,572,349 to 65,574,198, forward strand). Ensembl gene ENSG00000176973.
Subcellular location: Cytoplasm (Isoform 3); Cell projection, lamellipodium
Gene Ontology:
Molecular function: transcription corepressor binding
Biological process: establishment of cell polarity; negative regulation of SMAD protein signal transduction; negative regulation of transforming growth factor beta receptor signaling pathway; positive regulation of cell migration
Cellular component: cytoplasm; lamellipodium
Genetic constraint (gnomAD): Loss-of-function variants: 9 observed, 10.69 expected, observed/expected ratio (o/e) 0.84, 90% interval 0.51 to 1.46. The synonymous counts are far from expectation, so gnomAD's model fits this gene poorly and the ratio says little. Missense variants: 256 observed, 199.9 expected, observed/expected ratio (o/e) 1.28, 90% interval 1.16 to 1.42. Synonymous variants: 138 observed, 101.65 expected, observed/expected ratio (o/e) 1.36, 90% interval 1.18 to 1.56.
Homologues: Orthologues: dog FAM89B (96% identical), guinea pig FAM89B (96% identical), mouse Fam89b (96% identical), rat Fam89b (96% identical), macaque FAM89B (93% identical), chimpanzee FAM89B (56% identical), pig FAM89B (53% identical), zebrafish fam89b (48% identical), Drosophila melanogaster CG31038 (33% identical), Drosophila melanogaster lmgB (33% identical). Paralogues in human: FAM89A (43% identical), TRANK1 (37% identical).
Diseases named in the same sentence as FAM89B in open-access papers:
FAM89B is named in the same sentence as 5 diseases in open-access papers, as found by Europe PMC text mining. Sharing a sentence is not in itself a finding about the gene and the disease. The quoted sentences say what the papers report.
asthma (1 paper, 2024). "With respect to increased risk of asthma, blood genes again had the largest relative effect sizes in males (BAG6, CCNG, CRAT, PTPA, and FAM89B), with female training genes exhibiting the largest effects in ATP6V1G2 in the vastus lateralis, ENDOU in white adipose, and CCNF in blood." (PMID 38693125, 2024).
bladder cancer (1 paper, 2025).
pulmonary fibrosis (1 paper, 2022). Chronic progressive interstitial lung disorder characterized by the replacement of the lung tissue by connective tissue, leading to progressive dyspnea, respiratory failure, or right heart failure. "The third Top pathway had peak gene FAM89B, representing TGFβ signalling pathway, which is also associated with pulmonary fibrosis." (PMID 36203591, 2022).
tumor (1 paper, 2017). "Here, we detected a strong negative regulation of the TGF-β signaling pathway in tumor tissue after RNase A treatment, which was associated with the upregulation of Fam89b which is a TGF-β pathway suppressor (according to UniProt data, by sequence similarity)." (PMID 29108266, 2017).
FAM89B also shares sentences with these, for which no sentence is quoted: cystic fibrosis (1 paper).